TRPC6 (transient receptor potential cation channel subfamily C member 6)
Diseases named in the same sentence as TRPC6 in open-access papers (continued):
Sharing a sentence is not in itself a finding about the gene and the disease.
Duchenne muscular dystrophy (2 papers, 2017 to 2022). Duchenne muscular dystrophy (DMD) is a neuromuscular disease characterized by rapidly progressive muscle weakness and wasting due to degeneration of skeletal, smooth and cardiac muscle. "However, little is known about TRPC6 in skeletal muscle, although it is reported that myoblasts from mdx mice, a mouse model of Duchenne muscular dystrophy, shows a reduced expression of TRPC678." (PMID 29263348, 2017).
esophageal cancer (2 papers, 2015 to 2022). A primary or metastatic malignant neoplasm involving the esophagus. "Cox multivariate analysis showed that a high TRPC6 mRNA level was an independent risk factor for the prognosis of esophageal cancer." (PMID 35392906, 2022). "High TRPC6 expression has been observed in other cancers and was reported to be associated with poor prognosis of esophageal cancer." (PMID 26247464, 2015). "Sun Yat-sen University Cancer Center studied 172 cases of freshly frozen specimens after resection of esophageal cancer, and it was found that the expression of TRPC6 mRNA and protein was increased in esophageal cancer tissues compared with para-carcinoma tissues." (PMID 35392906, 2022).
fibrosis (2 papers, 2020 to 2021). the formation of excess fibrous connective tissue in an organ or tissue in a reparative or reactive process. "Fibrosis damage was alleviated in TRPC6−/− mice after UUO and in primary TEC treated with TGF-β1." (PMID 33520986, 2020).
gastric tumor (2 papers, 2018 to 2020). "Additionally, a newly developed TRPC6 inhibitor showed an anti-tumor effect in nude mice with a xenografted human gastric tumor." (PMID 32182937, 2020). "Moreover, treatment of nude mice with a TRPC6 blocker resulted in the inhibition of the development of a xenografted human gastric tumor." (PMID 32182937, 2020).
Hypercholesterolemia (2 papers, 2023 to 2024). An increased concentration of cholesterol in the blood. "The activation of TRPC6 and TRPC5 inhibits re-endothelialization of arterial injury in mice with hypercholesterolemia." (PMID 38703717, 2024).
hypertrophic pyloric stenosis (2 papers, 2011 to 2020). An abnormality characterized by thickening of the muscle in the wall of the pylorus. "Two SNPs, one in the promoter region of TRPC6 (rs3922961), the other in intron (rs7118839) together with a missense mutation in exon 4 (A404V) were found to underlie infantile hypertrophic pyloric stenosis (IHPS)." (PMID 31936014, 2020).
Insulin resistance (2 papers, 2019 to 2020). Increased resistance towards insulin, that is, diminished effectiveness of insulin in reducing blood glucose levels. "These authors reported enhanced p38 and cyclooxygenase 2 signaling along with gradual development of insulin resistance in Trpc6 knockout mice, which overcame the initial protective effects observed when the animals were younger." (PMID 32123821, 2019).
muscular dystrophy (2 papers, 2012 to 2020). Muscular dystrophy (MD) refers to a group of more than 30 genetic diseases characterized by progressive weakness and degeneration of the skeletal muscles that control movement. "The overexpression of a dominant negative mutant of TRPC6 in mdx or sarcoglycan-deficient mouse models of muscular dystrophy mitigates the dystrophic phenotype by inhibiting SOCE through TRPC6." (PMID 32244622, 2020). "TRPC function may contribute to the progression of muscular dystrophy as previous studies showed that by expressing a dominant negative TRPC6 could reduce the pathology in mdx and sarcoglycan null mice." (PMID 23185465, 2012). "TRPC6, as a SOCE channel, also is related to muscular dystrophy." (PMID 32244622, 2020).
Myocardial fibrosis (2 papers, 2021 to 2025). "Consistently, the orally bioactive TRPC6 inhibitor, BI 749327, was found to reduce the expression of profibrotic genes and blunt myocardial fibrosis in mice exposed to sustained pressure overload." (PMID 40149710, 2025). "Similarly, blocking the expression of TRPC6 with the bioactive compound Tinglu Yixin granule rescued cardiac function and tempered myocardial fibrosis in diabetic mice." (PMID 40149710, 2025). "Systolic blood pressure (SBP), heart rate, myocardial mass index (MMI), serum creatinine, cardiomyocyte diameter (dCM), myocardial fibrosis (MF), serum and kidney α-Klotho levels, myocardial expression of calcineurin (CaN), TRPC6, and β-catenin were measured two months after 5/6NE or SO." (PMID 33924991, 2021).
nephritis (2 papers, 2023 to 2024). Inflammation of renal tissue. "Mice overexpressing TRPC6 in podocytes demonstrated decreased podocyte foot effacement and proteinuria as compared to systemic TRPC6 knockout mice in nephrotoxic serum-induced nephritis." (PMID 38003608, 2023).
oesophageal cancer (2 papers, 2017 to 2019). "Several studies have shown a close correlation between TRPC6 channel overexpression and the development of cancers, such as prostate, breast, liver, brain, gastric, and oesophageal cancer." (PMID 31627357, 2019).
prediabetes (2 papers, 2013 to 2017). "TRPC6 mRNA was higher in patients with MA compared with the subjects with prediabetes and controls and higher in subjects with NO compared with controls." (PMID 24103534, 2013). "Moreover, in a study performed in patients with prediabetes and type 2 DM, podocyte marker expression was higher in diabetic subjects as compared to those with prediabetes with regard to mRNA of nephrin, podocin, podocalyxin, synaptopodin, TRPC6, alpha actinin-4, and TGF-β1." (PMID 28484521, 2017).
preeclampsia (2 papers, 2024). Preeclampsia is a hypertensive disorder of pregnancy that is characterized by new-onset hypertension with proteinuria presenting after 20 weeks of gestation, and depending on mild or severe forms may initially present with severe headache, visual disturbances, and hyperreflexia. "The results of the present study suggest that the variation in the TRPC6-related variant may affect not only preeclampsia, which occurs mainly in the second trimester of pregnancy but also cause NVP symptoms in early pregnancy." (PMID 38509478, 2024). "Furthermore, a variant near TRPC6, rs3018700 at 11q22, was associated with preeclampsia in a GWAS in a Finnish population." (PMID 38509478, 2024).
pulmonary disease (2 papers, 2020 to 2025). "Consistent with its broad expression in lungs, including bronchial epithelial cells, alveolar macrophages and pulmonary vasculature, TRPC6 contributes to pulmonary disorders, such as cystic fibrosis, asthma, pulmonary hypertension, COPD, lung edema, and lung fibrosis." (PMID 32139669, 2020). "TRPC6, a lipid-dependent membrane protein acting as non-selective cation channels conducting Na+ and Ca2+, is highly expressed in the lung and most studied in pulmonary diseases among TRPC channels." (PMID 32139669, 2020).
renal carcinoma (2 papers, 2022 to 2025). A carcinoma arising from the epithelium of the renal parenchyma or the renal pelvis. "Indeed, in our experiments, AC1903 inhibited multiple TRPC channels including TRPC3, TRPC4, TRPC5, TRPC6, TRPC4–C1, and TRPC5–C1, as well as endogenous TRPC1:C4 channels in A498 renal cancer cells, all with low micromolar IC50 values (1.8–18 μM)." (PMID 34999117, 2022).
systemic lupus erythematosus (2 papers, 2020 to 2023). An autoimmune multi-organ disease typically associated with vasculopathy and autoantibody production. "Patients with systemic lupus erythematosus (SLE) carrying a SNP in TRPC6 intron (rs7925662) was found to be prone to develop neuropsychiatric manifestations (NPSLE)." (PMID 31936014, 2020).
Adult onset (1 paper, 2024). Onset of disease manifestations in adulthood, defined here as at the age of 16 years or later. "The commonest genes affected in adult-onset FSGS (COL4A3–COL4A5,GLA ) have ocular abnormalities but not the other frequently affected genes (ACTN4, CD2AP, INF2, TRPC6)." (PMID 37578539, 2024).
Alport syndrome (1 paper, 2020). A rare renal disease characterized by glomerular nephropathy with hematuria progressing to end-stage renal disease (ESRD), frequently associated with sensorineural deafness, and occasionally with ocular anomalies. "We found there were no clinical features of Alport syndrome not only in six probands with c.2858G>T(p.(G953V)) in COL4A5 plus pathogenic variants in other genes (e.g., WT1, ADCK4, NPHP1, TRPC6, COL4A4, and PAX2) but also in another six probands with only the c.2858G>T(p.(G953V)) variant." (PMID 31576025, 2020).
anemia (1 paper, 2022). A reduction in the number of red blood cells, the amount of hemoglobin, and/or the volume of packed red blood cells. "Thus, a reduced level of TRPC6 expression due to the loss of DOT1L in erythroid progenitor cells may result in lethal anemia despite normal EPO signaling." (PMID 35563527, 2022).
autosomal dominant polycystic kidney disease (1 paper, 2014). Autosomal dominant form of polycystic kidney disease. "Mutations in transient receptor potential canonical 6 (TRPC6) channels and polycystin-2, a prototypical member of a subfamily of the TRPC channel superfamily, have been reported to cause familial focal segmental glomerulosclerosis and autosomal dominant polycystic kidney disease, respectively." (PMID 24745010, 2014).
brain infarct (1 paper, 2017). "We found that TRPC6 expression was increased in wild-type (WT) mice cortical neurons following I/R and in primary neurons with OGD, and that deletion of TRPC6 reduced the I/R-induced brain infarct in mice and the OGD- /neurotoxin-induced neuronal death." (PMID 28400714, 2017). "To determine whether TRPC6 plays a role in the brain infarct size, we employed the I/R model in WT and TRPC6−/− mice." (PMID 28400714, 2017).
brain tumours (1 paper, 2022). "Among these TRP family genes, it has been shown previously that TRPV2 in brain tumours, TRPV6 in PRAD, and TRPC6 in STAD promote tumour progression—which validates our analysis." (PMID 35493463, 2022).
bronchoconstriction (1 paper, 2022). Bronchoconstriction involves narrowing of air passage lumina, typically due to bronchial smooth muscle contraction, and leads to decreased air flow. "Most interestingly, the deletion of TRPC6 in TRPC6−/− mice resulted in a compensatory up-regulation of TRPC3 channels in tracheal smooth muscle cells and a subsequent increase in allergic bronchoconstriction (and see Section 2.2)." (PMID 36139480, 2022).
carotid artery thrombosis (1 paper, 2015). Blood clot formation in any part of the carotid arteries. "In the last set of studies, we examined the contribution of TRPC6 to thrombogenesis, using a FeCl3-induced carotid artery thrombosis model." (PMID 25928636, 2015).
Chronic Fatigue Syndrome (1 paper, 2020). "A SNP found in TRPC6 intron (rs11224816) together with SNPs in other TRP channels and acetylcholine receptor were suggested to be associated with Myalgic Encephalomyelitis (ME)/Chronic Fatigue Syndrome (CFS)." (PMID 31936014, 2020).
clear cell renal cell carcinoma (1 paper, 2020). "In addition, overexpression of TRPC6 in turn resulted in the nuclear translocation of NFAT (D1, D2 and E), suggesting this feedback loop between NFATc1 and TRPC6 exists in tubular cells in DN, like in podocytes, cardiomyocytes and clear cell renal cell carcinoma (ccRCC) cells." (PMID 32779844, 2020).
colitis (1 paper, 2024). Inflammation of the colon. "We observed an increase in the TRPC6 expression level in DSS-induced colitis mice compared to the control mice." (PMID 38397074, 2024). "Systemic TRPC3 knockout (KO) and TRPC6 KO mice were treated with dextran sulfate sodium (DSS) to induce colitis." (PMID 38397074, 2024). "Treatment with TRPC6 activator prevented the DSS-induced colitis progression accompanied by increasing Zn2+ concentration." (PMID 38397074, 2024). "Here, we examine the role of TRPC6 channels in colitis progression using dextran sulfate sodium (DSS)-treated TRPC6 KO mice and explore whether activation of TRPC6 channels prevents colitis progression by maintaining Zn2+ homeostasis." (PMID 38397074, 2024). "Drugs that promote TRPC6-mediated Zn2+ influx may be a breakthrough strategy to prevent colitis progression by maintaining gut systemic homeostasis." (PMID 38397074, 2024). "In other words, one possible reason for the worsening of DSS-induced colitis in TRPC6 KO mice might be the induction of reductive stress by antioxidant proteins." (PMID 38397074, 2024). "We finally examined whether the activation of TRPC6 improves colitis." (PMID 38397074, 2024). "We suggest that TRPC6-mediated Zn2+ influx activity plays a key role in stress resistance against IBD, providing a new strategy for treating colitis." (PMID 38397074, 2024). "To determine whether TRPC6-mediated Zn2+ affects the development of intestinal inflammation, we conducted experiments using whole-body TRPC3 knockout (KO) and TRPC6 KO mice in the DSS-induced colitis model." (PMID 38397074, 2024).
COVID-19 (1 paper, 2022). A disease caused by infection with severe acute respiratory syndrome coronavirus 2. "Importantly, a member of the same TRPC6 inhibitor class has been tested in humans (healthy men, NCT04665700, NCT03854552; renal disease, NCT04176536; and COVID-19, NCT04604184), enhancing the translational significance of our findings." (PMID 36099033, 2022).
dilated cardiomyopathy (1 paper, 2021). Cardiomyopathy which is characterized by dilation and contractile dysfunction of the left and right ventricles. "Measures of left ventricular end diastolic and left ventricular end systolic diameters (LVEDD, LVESD) used to determine cardiac dilatation showed that neither doxorubicin nor Trpc6 deficiency led to dilated cardiomyopathy at this time point in males." (PMID 35096991, 2021).
Dystonia (1 paper, 2021). An abnormally increased muscular tone that causes fixed abnormal postures. "Specifically, our laboratory previously detected abnormal expression of TRPC6 in the cerebellum of dystonia-like behaviors and motor dysfunction of autistic BTBR mice." (PMID 34327201, 2021).
edema (1 paper, 2022). An abnormal accumulation of fluid beneath the skin, or in one or more cavities of the body. "Overall, downregulation of PN production and blockade of non-selective cation channels (TRPC6 and TRPM4) could relieve pulmonary edema in ARDS." (PMID 35794575, 2022).
emphysema (1 paper, 2022). "Thus, e.g., TRPV4 channels are essential for alveolar epithelial barrier function as protection from lung edema and lungs from mice lacking TRPC6 are protected from lung ischaemia-reperfusion-induced oedema (LIRE), while magnesium deficiency in TRPM6 results in severe emphysema." (PMID 35053420, 2022).
Hearing impairment (1 paper, 2012). A decreased magnitude of the sensory perception of sound. "Double TRPC3/TRPC6 knock-out mice also showed hearing impairment, vestibular deficits and defective auditory brain stem responses to high-frequency sounds." (PMID 22724068, 2012).
Hypercalciuria (1 paper, 2025). "The TRPC5 and TRPC6 (transient receptor potential) channels play a key role in the renal reabsorption of calcium; mice lacking these proteins suffer from hypercalciuria and bone disease." (PMID 40218942, 2025).
Hyperinsulinemia (1 paper, 2021). An increased concentration of insulin in the blood. "Orai1 overexpression was prominent only at the early stage coinciding with hyperinsulinemia, while a higher expression of TRPC6 was obvious at the late stage." (PMID 34764278, 2021).
hyperkalaemia (1 paper, 2022). "After IRI, WT and Trpc6 deficient mice developed similar hyperkalaemia and similar high serum levels of creatinine and urea nitrogen." (PMID 35194063, 2022).
Interstitial cardiac fibrosis (1 paper, 2019). A type of myocardial fibrosis characterized by excessive diffuse collagen accumulation concentrated in interstitial spaces. "Recently, chronic treatment of rat models of pressure overload with GSK503A, proposed to inhibit both TRPC3 and TRPC6, showed no interstitial cardiac fibrosis, suggesting that TRPC3 and TRPC6 are needed for the fibrosis appearance." (PMID 30881310, 2019).
intracranial aneurysm (1 paper, 2023). "In intracranial aneurysm, a VSMC phenotypic switch is reported that is mediated by increased TRPC6, calcineurin and NFaT expression that leads to enhanced NOX4, p22phox and p47phox expression and ROS production followed by the progression of intracranial aneurysm." (PMID 37759492, 2023).
lentivirus infection (1 paper, 2018). Virus diseases caused by the Lentivirus genus. "After sh-TRPC6 lentivirus infection, the mRNA and protein expression of TRPC6 were downregulated." (PMID 30282964, 2018).
leukemia (1 paper, 2021). A malignant (clonal) hematologic disorder, involving hematopoietic stem cells and characterized by the presence of primitive or atypical myeloid or lymphoid cells in the bone marrow and the blood. "Among the other genes with strong correlations between DNA methylation and gene expression, aberrant DNA methylation and downregulation of FKBP9, CA8, MSC, TRPC6, ZNF492, ZNF229, and ZNF471 genes in leukemia patients are reported here for the first time." (PMID 34575904, 2021).
lung squamous cell carcinoma (1 paper, 2013). "In lung squamous cell carcinoma sections, the squamous cells were strongly stained with anti-TRPC1, anti-TRPC3, anti-TRPC4 and anti-TRPC6 antibodies." (PMID 23840757, 2013).
lymphoma (1 paper, 2024). A malignant (clonal) proliferation of B- lymphocytes or T- lymphocytes which involves the lymph nodes, bone marrow and/or extranodal sites. "Of particular interest would be an immunohistochemical study of TRPC6 in lymphoma cells or the staining of lymph nodes of septic patients, with a direct comparison to physiological tissue." (PMID 39161881, 2024). "In addition to lymphoma cells, a connection has been established between TRPC6 and tumor entities, such as breast, cervical, gastric, esophageal cancer and gliomas." (PMID 39161881, 2024).